EGR4 (early growth response 4)
Description:
Transcriptional regulator. Recognizes and binds to the DNA sequence 5'-GCGGGGGCG-3' (GSG). Activates the transcription of target genes whose products are required for mitogenesis and differentiation (By similarity).
Synonyms: NGFI-C; PAT133; AT133; NGFIC
Tractability: No criterion of Open Targets' tractability assessment is met for any kind of drug.
Gene: Protein-coding gene on chromosome 2 (73,290,927 to 73,293,721, reverse strand). Ensembl gene ENSG00000135625.
Subcellular location: Nucleus
Pathways (Reactome):
Signal Transduction: NGF-stimulated transcription
Gene Ontology:
Molecular function: DNA-binding transcription activator activity, RNA polymerase II-specific; protein binding; sequence-specific DNA binding; sequence-specific double-stranded DNA binding; DNA-binding transcription factor activity; DNA-binding transcription factor activity, RNA polymerase II-specific; RNA polymerase II cis-regulatory region sequence-specific DNA binding
Biological process: positive regulation of transcription by RNA polymerase II; positive regulation of cell population proliferation; regulation of transcription by RNA polymerase II
Cellular component: chromatin; nucleoplasm; nucleus
Genetic constraint (gnomAD): Loss-of-function variants: 22 observed, 20.05 expected, observed/expected ratio (o/e) 1.1, 90% interval 0.78 to 1.56. The synonymous counts are far from expectation, so gnomAD's model fits this gene poorly and the ratio says little. Missense variants: 742 observed, 609.21 expected, observed/expected ratio (o/e) 1.22, 90% interval 1.15 to 1.29. Synonymous variants: 375 observed, 280.13 expected, observed/expected ratio (o/e) 1.34, 90% interval 1.23 to 1.46.
Homologues: Orthologues: chimpanzee EGR4 (99% identical), macaque EGR4 (98% identical), rabbit EGR4 (92% identical), pig EGR4 (90% identical), dog EGR4 (89% identical), guinea pig EGR4 (89% identical), rat Egr4 (86% identical), mouse Egr4 (85% identical), tropical clawed frog egr4 (40% identical), zebrafish egr4 (25% identical), zebrafish egr1 (24% identical), zebrafish egr2a (21% identical), and 2 more. Paralogues in human: EGR1 (26% identical), EGR2 (26% identical), EGR3 (24% identical), WT1 (17% identical).